PSRC1 (proline and serine rich coiled-coil 1)
Description:
Required for normal progression through mitosis. Required for normal congress of chromosomes at the metaphase plate, and for normal rate of chromosomal segregation during anaphase. Plays a role in the regulation of mitotic spindle dynamics. Increases the rate of turnover of microtubules on metaphase spindles, and contributes to the generation of normal tension across sister kinetochores. Recruits KIF2A and ANKRD53 to the mitotic spindle and spindle poles.
Synonyms: DDA3; FP3214
Tractability: No criterion of Open Targets' tractability assessment is met for any kind of drug.
Gene: Protein-coding gene on chromosome 1 (109,279,545 to 109,284,107, reverse strand). Ensembl gene ENSG00000134222.
Subcellular location: Cytoplasm; Cytoplasm, cytoskeleton, spindle; Cytoplasm, cytoskeleton, spindle pole
Subcellular location (Human Protein Atlas): Cytosol; Nucleoplasm
Gene Ontology:
Molecular function: protein binding; microtubule binding
Biological process: mitotic metaphase chromosome alignment; regulation of mitotic spindle organization; microtubule bundle formation; negative regulation of cell growth; positive regulation of DNA-templated transcription; positive regulation of microtubule polymerization
Cellular component: cytosol; spindle microtubule; spindle pole; cytoplasm; microtubule cytoskeleton; midbody; spindle
Genetic constraint (gnomAD): Loss-of-function variants: 30 observed, 31.8 expected, observed/expected ratio (o/e) 0.94, 90% interval 0.7 to 1.28. The upper end of that interval is the gene's LOEUF score, 1.28, which puts it in group 5 of 6, group 1 being the genes least tolerant of losing a copy. Missense variants: 481 observed, 480.26 expected, observed/expected ratio (o/e) 1, 90% interval 0.93 to 1.08. Synonymous variants: 191 observed, 194.82 expected, observed/expected ratio (o/e) 0.98, 90% interval 0.87 to 1.11.
Homologues: Orthologues: chimpanzee PSRC1 (99% identical), macaque PSRC1 (96% identical), rabbit PSRC1 (86% identical), dog PSRC1 (86% identical), pig PSRC1 (83% identical), guinea pig PSRC1 (81% identical), mouse Psrc1 (70% identical), rat Psrc1 (70% identical). Paralogues in human: GTSE1 (25% identical).
Diseases named in the same sentence as PSRC1 in open-access papers:
PSRC1 is named in the same sentence as 35 diseases in open-access papers, as found by Europe PMC text mining. Sharing a sentence is not in itself a finding about the gene and the disease. The quoted sentences say what the papers report.
coronary artery disease (15 papers, 2014 to 2026). "Genome-wide association studies have implicated proline/serine-rich coiled-coil 1 (PSRC1) in coronary artery disease (CAD) pathogenesis." (PMID 41792233, 2026). "Proline/serine‐rich coiled‐coil protein 1 (PSRC1) is a key factor associated with the regulation of immune responses and coronary artery disease (CAD) development." (PMID 40027477, 2025). "For example, the ALT-increasing allele rs1277930-A (near PSRC1) associates with increased dyslipidemia and coronary artery disease at genome-wide significance for example." (PMID 33547301, 2021). "CELSR2 and PSRC1 (rs599839) have been associated with both coronary artery disease and total cholesterol concentration." (PMID 24725463, 2014). "Our results suggest that the rs599839 polymorphism of the PSRC1 gene could participate in the development of cardiovascular diseases and mainly in the genetic predisposition to coronary artery disease." (PMID 36975855, 2023). "For example, among the candidate genes were known susceptibility loci for diabetes (PTPN22, CEP68, RREB1, TCF7L2), coronary artery disease (PSRC1, UNC5C, LPLA), depression (MAD1L1, YLPM1) and insomnia (NMT1)." (PMID 38541061, 2024). "In 2007, Samani published a genome‐wide association study on coronary artery disease (CAD), and this study first identified the association of PSRC1 gene polymorphisms with the development of CAD." (PMID 36932468, 2023). "The PSRC1-CELSR2-SORT1 locus, best known for its associations with coronary artery disease and cholesterol levels, showed enrichment for protein associations with bone mineral density." (PMID 35078996, 2022). "Evidence from multi‐omics layers of data consistently supports PSRC1 with therapeutic potential for coronary artery disease (CAD), but not ischemic stroke." (PMID 39985383, 2025).
atherosclerosis (11 papers, 2020 to 2026). A disease characterized by the build-up of fatty material and calcium deposition in the arterial wall resulting in partial or complete occlusion of the arterial lumen. "Our previous studies demonstrated that Psrc1 deficiency accelerates atherosclerosis via gut microbial dysbiosis, characterized by a substantial depletion of Akkermansia muciniphila." (PMID 41792233, 2026). "PSRC1 deficiency in ApoE-/- mice accelerated atherosclerosis by boosting TMAO, increased TMA-producing bacteria and plasma betaine and TMAO levels." (PMID 40356907, 2025). "Then, FMT was performed to clarify the underlying influence of microbial gut dysbiosis induced by PSRC1 deletion on atherosclerosis." (PMID 35613310, 2022). "Considering the association between gut microbiota and atherosclerosis, we sought to investigate the impact of PSRC1 deletion on the gut microbiota, especially the TMAO generation-related bacteria." (PMID 35613310, 2022). "Collectively, these results suggested that the regulation of the gut microbiota may be the main cause of the atherosclerosis-protective role of PSRC1 in this study." (PMID 35613310, 2022). "Thus, PSRC1 deficiency accelerates the development of HFD-induced atherosclerosis." (PMID 35613310, 2022). "The overexpression of PSRC1 reduces the macrophage inflammatory response and delays the development of atherosclerosis." (PMID 39334763, 2024). "It is reported PSRC1 functions in the molecular path that mediates the impact of a TMAO-rich diet on atherosclerosis." (PMID 37274792, 2023). "Upregulated PSRC1 contributed to reduce the atherosclerosis by regulating the cholesterol transportation in apoE-/- mice." (PMID 35685372, 2022). "Overall, we identified PSRC1 as an atherosclerosis-protective factor, at least in part, attributable to its regulation of TMAO generation via a multistep pathway." (PMID 35613310, 2022). "Notably, oral IAA supplementation substantially ameliorated atherosclerosis in Psrc1 knockout mice by suppressing plaque macrophage apoptosis." (PMID 41792233, 2026). "The mechanism by which Psrc1 modulates atherosclerosis through A. muciniphila and its regulation of tryptophan metabolism remains unclear." (PMID 41792233, 2026). "Furthermore, therapeutic restoration of a live A. muciniphila-IAA axis through oral supplementation reversed atherosclerosis in Psrc1 knockout mice." (PMID 41792233, 2026). "PSRC1 deficiency elevates TMAO and worsens atherosclerosis in ApoE-/- mice through gut dysbiosis." (PMID 40356907, 2025). "In agreement with our previous study on the role of PSRC1 in atherosclerosis, double-knockout of PSRC1 and apoE significantly accelerated plaque formation compared with apoE knockout mice, reconfirming the atherosclerosis-protective effect of PSRC1." (PMID 35613310, 2022). "Thus, PSRC1 holds great potential for manipulating the gut microbiome and alleviating atherosclerosis." (PMID 35613310, 2022). "To address this hypothesis, we first confirmed an atherosclerosis-protective role of PSRC1 in high-fat diet (HFD) fed-mice models." (PMID 35613310, 2022). "Moreover, PSRC1 was shown to protect against atherosclerosis and enhance the stability of atherosclerotic plaques in Apoe-/- mice by modulating cholesterol transportation and inflammation." (PMID 32591598, 2020). "Our studies reveal an emerging role for global PSRC1 in TMAO generation and provide potential therapeutic approaches for atherosclerosis." (PMID 35613310, 2022). "Here, we investigated the impact of PSRC1 deletion on TMAO generation and atherosclerosis." (PMID 35613310, 2022). "In summary, our work sheds light on the influence of PSRC1 on atherosclerosis in the mouse models independent of the known lipid metabolism and inflammatory pathways." (PMID 35613310, 2022).
atherosclerosis (continued). "Moreover, polymorphism of the genomic region-rs646776 within the cadherin endothelial growth factor (EGF) LAG seven-pass G-type receptor 2 (CELSR2), proline/serine-rich coiled-coil 1 (PSRC1), and sortilin 1 (SORT1) gene cluster is related to dyslipidemia and atherosclerosis." (PMID 36913212, 2023). "Firstly, we performed the study using double-knockout mouse model to describe the metagenome signature of PSRC1 deletion in the context of atherosclerosis; however, the response may not exclude the pro-inflammatory environment induced by apoE deficiency." (PMID 35613310, 2022).
dyslipidemia (9 papers, 2011 to 2025). "We noted higher methylation at this site lowers the level of PSRC1 (β = −0.24, p = 3.7e−192) and as the expression of this gene decreases the risk of dyslipidemia and CAD increases." (PMID 37274792, 2023). "To determine whether the rs599839 polymorphisms of the PSRC1 gene were independent parameters for CAD, we adjusted confounding risk factors, such as age, sex, body mass index, smoking, dyslipidemia, diabetes, and hypertension." (PMID 38028723, 2023). "Rs12740374 in CELSR2/PSRC1/SORT1 cluster was associated with two lipid traits: total cholesterol and dyslipidemia in our study, which is closely related with previously reported associations with LDL cholesterol and lipoprotein-associated phospholipase A2 activity and mass." (PMID 30704471, 2019).
diabetes (6 papers, 2015 to 2026). "In the multivariate logistic regression analysis, the following variables were included: SLC30A8 (CC), PSRC1 (AA + GA), KIF6 (CC), diabetes, age, smoking, hypertension, dyslipidaemia, BMI, and physical inactivity." (PMID 41009965, 2025).
myocardial infarction (5 papers, 2016 to 2024). Gross necrosis of the myocardium, as a result of interruption of the blood supply to the area, as in coronary thrombosis. "In this regard, Matsuoka, R., 2015 found an association between the rs599839 polymorphism (PSRC1, FDR = 0.0118) and myocardial infarction in the Asian population." (PMID 36975855, 2023). "For example, one of the strongest associations for myocardial infarction lies in-between the CELSR2 and PSRC1 genes on chromosome 1p13, but a careful screen of genes whose expression was affected by the risk allele implicated the more distal SORT1 gene." (PMID 29988018, 2018). "Additionally, SP1 may offer protection against coronary atherosclerosis and cardiac remodeling post-myocardial infarction by influencing the gene transcription of PSRC1, ABCA1, SR-BI, and P4Ha1." (PMID 39062521, 2024).
hepatocellular carcinoma (3 papers, 2022 to 2024). A malignant tumor that arises from hepatocytes. "Interestingly, we found long-term survival of HBV leads to down-regulated expression levels of F11 and FBP1 mRNAs but up-regulated PSRC1 mRNA in HBV-replicating hepatocellular carcinoma cell lines." (PMID 36212461, 2022). "Five genes (PSRC1, SOCS2, TMEM45A, CCT5, and STC2) were selected from the TCGA training dataset to construct the prognostic CSGscore signature, which could precisely predict the prognosis of hepatocellular carcinoma patients both in the training and validation datasets." (PMID 36589233, 2022).
hepatic cancer (2 papers, 2021). "Interestingly, in TCGA dataset the overexpression of PSRC1 has been strictly correlated with poor prognosis, tumor stage, advanced grade, and increased size of liver cancers, further reinforcing what we have observed in our cohort of NAFLD-HCC patients." (PMID 33917919, 2021).
lung carcinoma (2 papers, 2013 to 2023). "This study aimed to investigate the biological function and prognostic value of proline- and serine-rich coiled-coil 1 (PSRC1) in lung cancer." (PMID 37928428, 2023). "Over-expression of Psrc1 has been shown to suppress colony formation in lung carcinoma cells." (PMID 23533623, 2013).
Lung squamous cell carcinoma (2 papers, 2023 to 2024). "The relationship between PSRC1 expression and prognosis in lung adenocarcinoma (LUAD) and lung squamous cell carcinoma (LUSC) was analyzed using Kaplan-Meier curves." (PMID 37928428, 2023).
non-small cell carcinoma (2 papers, 2023 to 2024). "In addition, the expression of PSRC1 in 150 patients with non-small cell carcinoma was detected using immunohistochemistry, and its clinical significance was analyzed." (PMID 37928428, 2023). "Moreover, the survival analysis has demonstrated that the elevated expression of PSRC1 correlates with a lower survival rate in SCLC, which aligns with the circumstances observed in non-small cell lung cancer." (PMID 39872525, 2024). "Interestingly, a potential link between PSAT1 and PSRC1 has been found in previous studies of non-small cell lung cancer, in which increased PSAT1 expression inhibits the degradation of the cell cycle protein d1, while elevated PSRC1 expression promotes the production of this protein." (PMID 39872525, 2024).
Stroke (2 papers, 2016 to 2025). Sudden impairment of blood flow to a part of the brain due to occlusion or rupture of an artery to the brain. "This analysis identified 17 genes expressed in the blood that were associated with RA and one gene, proline/serine-rich coiled-coil protein 1 (PSRC1), which is also expressed in blood and associated with stroke." (PMID 39953635, 2025).
central obesity (1 paper, 2025). "PSRC1 rs599839 in a dominant model (AA + GA vs. GG) with OR = 3.18 (p = 0.041), SLC30A8 rs1326634 in a recessive model (CC vs. TC + TT) (OR = 2.38; p = 0.004), both showing increased susceptibility to central obesity." (PMID 41009965, 2025).
cerebrovascular disease (1 paper, 2022).
psoriasis (1 paper, 2020). An autoimmune condition characterized by red, well-delineated plaques with silvery scales that are usually on the extensor surfaces and scalp. "Nevertheless, further support for the relationship between PSRC1 and progranulin emerges from reports on progranulin-deficient mice and patients with psoriasis, where progranulin was negatively correlated with ß-catenin expression in psoriatic skin lesions." (PMID 32620998, 2020).
tumor (7 papers, 2021 to 2023). "In HCC, the expression of PSRC1 was found to be positively associated with cell proliferation and tumor development." (PMID 36589233, 2022). "Likewise, PSRC1 overexpression has been previously detected in tumor liver tissues and in hepatoma cells, where it is associated with HCC recurrence after resection." (PMID 33917919, 2021). "Nonetheless, we found 46 genes that carried either genomic or transcriptional alterations in all three resistant tumor groups, including 8 genes (Parp3, Gstm1, Il18, Padi4, Dnmt3b, Psrc1, Rif1, and Ankrd26) involved in DDR." (PMID 37209095, 2023). "Functional enrichment analysis showed that PSRC1 is related to tumor development." (PMID 37928428, 2023). "The PSRC1 sub-network was significantly enriched in the Cell Cycle category, suggesting that this gene may have a tumor-promoting effect in SCLC." (PMID 37958393, 2023). "Similarly, the rs599839 A > G variant, which causes the overexpression of the oncogene Proline And Serine Rich Coiled-Coil 1 (PSRC1), has been associated with enhanced HCC risk in NAFLD patients, irrespectively of fibrosis severity, and with poor prognosis and advanced tumor stage." (PMID 34680476, 2021). "Moreover, F11 decreases but PSRC1 increases cell proliferation of HBV-containing HCC cells, indicating their potential tumor-suppressive and promoting function in HCC development, respectively." (PMID 36212461, 2022).
cancer (6 papers, 2015 to 2024). A tumor composed of atypical neoplastic, often pleomorphic cells that invade other tissues. "Pathways associated with cancer are also enriched in the C+/+/Tia1−/− testis, and the genes Psrc1, Ano3 and Zfp365, all upregulated in C+/+/Tia1−/− testis, are regulated by the tumor suppressor p5368–70." (PMID 28775379, 2017). "In UKKBC there is not individual data available about cancer history, thus precluding a formal evaluation of the interaction between PSRC1 and the risk of HCC in this population." (PMID 33917919, 2021).
cardiovascular diseases (2 papers, 2022 to 2023). "A cluster of three genes CELSR2, PSRC1, and SORT1 has been associated with cardiovascular diseases." (PMID 36975855, 2023).
PSRC1 also shares sentences with these, for which no sentence is quoted: Obesity (4 papers); breast carcinoma (3); Hypertension (3); pancreatic cancer (2); aortic stenosis (1); atopic dermatitis (1); Cirrhosis (1); coronary atherosclerosis (1); depression (1); Disorder of lipid metabolism (1); dyslipidaemia (1); Fanconi anemia (1); glioma (1); gout (1); hyperlipidemia (1); insomnia (1); liver disease (1); lung adenocarcinoma (1).